TTR (transthyretin)
Diseases named in the same sentence as TTR in open-access papers (continued):
Sharing a sentence is not in itself a finding about the gene and the disease.
axonal neuropathy (3 papers, 2021 to 2022). Any nerve disorder affecting the axon of a nerve. "The aim of this study was to arrange a clinical and electrophysiological score to select patients with axonal neuropathy that deserve screening for TTR mutation." (PMID 35279758, 2022). "Recognizing that these case numbers were too low to be representative for statistical analyses, the UPSS still tended to be higher in symptomatic patients compared to pre-symptomatic TTR mutation carriers and to other axonal neuropathy patients (CMT2, mean = 1.33 ± 1.45)." (PMID 34708324, 2021). "The TTR-FAP was an axonal neuropathy and the loss of nerve fibers was diffuse and regular." (PMID 33716932, 2021). "Transthyretin-mutated protein accumulates mainly in heart and peripheral nervous system (PNS), leading cardiomyopathy and progressive axonal peripheral neuropathy, respectively." (PMID 35279758, 2022). "The aim of this study was to optimize a clinical and electrophysiological score to select patients with axonal neuropathy worthy of TTR screening." (PMID 35279758, 2022). "Moreover, prominent enlargement of peripheral nerves at proximal sites was not common in most axonal neuropathies, which could help distinguish TTR-FAP from other axonal neuropathies." (PMID 33716932, 2021).
cerebrovascular disease (3 papers, 2020 to 2025). "TTR stabilization seems also important to prevent pathological changes to the brain vasculature, and for example, heterozygous individuals with TTR T119M allele, which renders a more stable tetramer, have a reduced risk of cerebrovascular disease compared to homozygotes for WT TTR." (PMID 34429155, 2021).
colorectal cancer (3 papers, 2023 to 2025). A primary or metastatic malignant neoplasm that affects the colon or rectum. "Comparative analysis revealed that the TTR-higher group exhibited a younger demographic, a higher prevalence of low colorectal cancers, an elevated R0 resection rate, superior differentiation, earlier stage and lower levels of carcinoembryonic antigen (CEA) in contrast to the TTR-lower group." (PMID 39975596, 2025).
coronary atherosclerosis (3 papers, 2020 to 2022). Atherosclerosis of the coronary vasculature. "But in an earlier study, an increase in the content of transthyretin, hemopexin and retinol-binding protein-4 was found in blood serum samples of patients with verified coronary atherosclerosis." (PMID 34948066, 2021). "Proteome profiling of serum revealed a change in the content of kininogen, hemopexin, transthyretin, retinol-binding protein, and proteins of the complement system (C9, and C3) in coronary atherosclerosis." (PMID 33033454, 2020).
diabetic nephropathy (3 papers, 2010 to 2023). "Plasma potential biomarkers such as apolipoprotein C-I, apoA-I, transthyretin, and cystatin C were purposed to predict the progression and response to the treatment in diabetic kidney disease." (PMID 36865924, 2023). "Four of the peaks that were discovered have been identified as transthyretin, apolipoprotein A1, apolipoprotein C1 and cystatin C. Several yet unidentified proteins discovered by this novel approach appear to have more potential as biomarkers for diabetic nephropathy." (PMID 20205888, 2010).
endothelial dysfunction (3 papers, 2023 to 2025). In vascular diseases, endothelial dysfunction is a systemic pathological state of the endothelium (the inner lining of blood vessels) and can be broadly defined as an imbalance between vasodilating and vasoconstricting substances produced by (or acting on) the endothelium. "In the current study, adiposome levels of TTR demonstrated inverse correlations with visceral adiposity, systemic inflammation, and endothelial dysfunction, as well as a strong direct correlation with flow-mediated vasodilation." (PMID 40981199, 2025).
erectile dysfunction (3 papers, 2021 to 2025). Persistent or recurrent inability to achieve or to maintain an erection during sexual activity. "ATTR, transthyretin; ED, erectile dysfunction; GI, gastro-intestinal; CT, computed tomography." (PMID 39687736, 2024).
gastric adenocarcinoma (3 papers, 2012 to 2024). "Western blotting also showed high expression of SPINK4, TTR, PCSK1N, CHGA and GHRL in gastric adenocarcinoma cell lines, with GHRL showing the most significant increase (p < 0.05)." (PMID 38752750, 2024). "Two panels of combinatorial biomarkers, including EGFR, TTR, RANTES, and VN, are developed, which are less invasive method for the diagnosis of gastric adenocarcinoma." (PMID 22240791, 2012).
glycogen storage disease (3 papers, 2018 to 2025). "Using this method, we detected the rare gene mutation-related glycogen storage disease and TTR infiltrative disease." (PMID 34362124, 2021).
Guillain-Barre syndrome (3 papers, 2008 to 2023). A spectrum of rare post-infectious neuropathies that usually occur in otherwise healthy patients. "TTR in CSF has been described as reduced in Guillain-Barré syndrome as well as in patients with meningioma." (PMID 37420193, 2023).
hemophilia (3 papers, 2022 to 2024). Hemophilia is a genetic disorder characterized by spontaneous hemorrhage or prolonged bleeding due to factor VIII or IX deficiency. "To study whether hFVa induces a phenotypic correction in a hemophilia setting, we constructed AAV8 vectors encoding hFVa driven by the TTR promoter (AAV8/TTR-hFVa)." (PMID 35991645, 2022). "In hemophilia B mice, a dose of 4 × 1013 vg/kg AAV8/TTR-hFVa vectors achieved a complete phenotypic correction over 28 weeks." (PMID 35991645, 2022). "In comparison to WT and untreated hemophilia mice, gene therapy with AAV8/TTR-hFVa did not induce increased risk of thrombosis based on normal TAT levels and fibrinolysis on ROTEM." (PMID 35991645, 2022).
Hepatitis (3 papers, 2013 to 2018). Inflammation of the liver. "Conclusively, the ALT serum levels were about five-fold reduced in the T cell-mediated hepatitis model after adenovirus infection with the TTR-driven as compared to the CMV-driven construct." (PMID 30442932, 2018).
injury (3 papers, 2017 to 2025). Damage inflicted on the body as the direct or indirect result of an external force, with or without disruption of structural continuity. "TTR plays a neuroprotective role in amyloid beta aggregation inhibition and protection from brain trauma, illustrating that CsA can also modulate neuroprotective genes by bringing them back to their levels of homeostasis." (PMID 40331981, 2025).
juvenile idiopathic arthritis (3 papers, 2017 to 2021). Juvenile idiopathic arthritis (JIA) is the term used to describe a group of inflammatory articular disorders of unknown cause that begin before the age of 16 and last over 6 weeks. "However, some Fezf2-dependent TRAs identified in mice are autoantigens in humans, including aquaporin 8 (AQP8) in Sjögren syndrome and transthyretin (TTR) in juvenile idiopathic arthritis (JIA)." (PMID 33537838, 2021). "Upregulation and high levels of aggregated and oxidized forms of TTR were detected in the plasma and synovial fluid in juvenile idiopathic arthritis (JIA)." (PMID 34359938, 2021).
liver dysfunction (3 papers, 2019 to 2025). "Prealbumin (PAB), also known as transthyretin (TTR), is synthesized by liver cells and is highly sensitive to detecting protein malnutrition and liver dysfunction due to its short half-life." (PMID 39937806, 2025).
liver failure (3 papers, 2010 to 2025). A liver disease characterized by the liver losing or has lost all of its function. "As the livers from FAP patients undergoing OLT are functionally normal, except for the production of a mutated TTR variant, the domino liver transplantation (DLT), in which FAP livers are transplanted to patients with liver failure, was recently introduced." (PMID 22053176, 2011). "Hepatocyte markers ALB, TTR and alcohol dehydrogenase 1A (ADH1A) were not significantly DE between normal and early ALD but were significantly downregulated in AH versus early ALD, suggesting a secondary transcriptomic response following onset of liver failure." (PMID 40122595, 2025).
memory impairment (3 papers, 2020 to 2025). "Studies on TTR KO mice showed the lack of TTR leads to an accelerated memory deficit with age, and, conversely, TTR expression is decreased in rats with age-related memory impairment." (PMID 39192044, 2025).
Miscarriage (3 papers, 2014 to 2023). A pregnancy that ends at a stage in which the fetus is incapable of surviving on its own, defined as the spontaneous loss of a fetus before the 22th week of pregnancy. "In particular, we found that abnormal maternal-fetal thyroid hormone transport caused by low expression of transthyretin in trophoblasts was involved in miscarriage." (PMID 37968664, 2023). "We propose the putative role of TTR in an increased risk of metabolic adversities among women with miscarriages and MeS." (PMID 30783564, 2019). "Accordingly, mRNA level of TTR in the placenta villi of miscarriage patients was decreased compared with that in controls." (PMID 37968664, 2023). "Though the history of miscarriage and MeS serve as independent risk factors for CVDs, the present study showed higher expression of TTR exclusively among women with a history of miscarriage and MeS." (PMID 30783564, 2019). "Networking analyses suggest cross talk between the four dysregulated proteins, that is, HP, TF, ApoA1, and TTR as a connecting link between miscarriage history and MeS." (PMID 30783564, 2019). "Other proteins that were significantly increased in the obese miscarriage group were transthyretin (pre-albumin), and beta globin." (PMID 25096020, 2014). "Our results showed lower expression of TTR and THRα in placenta villi in miscarriage cases." (PMID 37968664, 2023). "A cross talk between HP, ApoA1, TF, and TTR estabishs link between miscarriage and MeS." (PMID 30783564, 2019). "Similarly, the densitometric analysis of Western blots validated a significantly higher expression of TTR in absolute cases (1.56-fold), only MeS cases (1.33-fold) and only history of miscarriage (2.21-fold) as compared with absolute control." (PMID 30783564, 2019). "However, longitudinal follow-up studies with larger sample sizes would further help to demonstrate the involvement of TTR and significance of its cross-talk with other proteins in the occurrence of CVDs in women with a history of miscarriages and MeS." (PMID 30783564, 2019). "In miscarriage group, the gene expression of Dio2, Dio3, TTR and THRα, but not THRβ, MCT8 and OATP1A1, were downregulated." (PMID 37968664, 2023). "The protein abundances of TTR and THRα were downregulated in miscarriage group, but not THRβ." (PMID 37968664, 2023).
osteoporosis (3 papers, 2021 to 2025). A condition of reduced bone mass, with decreased cortical thickness and a decrease in the number and size of the trabeculae of cancellous bone (but normal chemical composition), resulting in increased fracture incidence. "Inverse correlation between the levels of TTR and inflammation markers (hs-CRP) suggests a protective role of TTR in osteoporosis." (PMID 34359938, 2021). "Evidence suggests that stable TTR is necessary for healthy bone tissue development and that there is a relationship between TTR levels and osteoporosis; therefore, it is essential to investigate whether long-term suppression of TTR levels has an impact on bone health." (PMID 40717228, 2025).
ovarian tumor (3 papers, 2007 to 2014). "Existing research shows that TTR can be used as a member of the ovarian tumor marker spectrum." (PMID 25250314, 2014).
pancreatic neuroendocrine tumor (3 papers, 2017 to 2022). Pancreatic endocrine tumor, also known as pancreatic neuroendocrine tumor (PNET), describes a group of endocrine tumors originating in the pancreas that are usually indolent and benign, but may have the potential to be malignant. "TTR is also synthesized in the endocrine pancreas, liver, and choroid plexus of the brain, and endocrine pancreatic tumors contain TTR mRNA, corresponding to our previous microarray result." (PMID 29190982, 2017). "The expression patterns of MMP7 and TTR were also evaluated in vivo by performing an immunohistochemistry analysis of human CP samples and adjacent sections of morphologically normal pancreatic tissue obtained from patients with pancreatic neuroendocrine tumors." (PMID 35741777, 2022). "TTR and HP bound to fucose have been already proposed as a biomarkers of PDA; CDH5 in pancreatic neuroendocrine tumors developed in Von Hippel–Lindau disease patients and FCGBP in mucinous cysts in the pancreas and PDA." (PMID 32245227, 2020).
prediabetes (3 papers, 2018 to 2023). "TTR was associated with prediabetes and TG level, whereas RBP4 was only associated with TG." (PMID 29747616, 2018).
pulmonary hypertension (3 papers, 2022 to 2025). Increased pressure within the pulmonary circulation due to lung or heart disorder. "Our study explores the effects and molecular mechanisms through which TTR alleviates pulmonary hypertension from both the in vivo and the in vitro perspectives." (PMID 37149589, 2023).
small fiber neuropathies (3 papers, 2020 to 2023). "Subclinical ocular abnormalities detected by IVCM in TTR mutation carriers could be early expression of small fiber neuropathy (SFN)." (PMID 36766465, 2023). "In our clinic population, an additional 48 patients, including 4 patients with pure small fiber neuropathy, had already been screened for TTR gene mutations prior to our study, and had negative results." (PMID 32493526, 2020). "The Scandinavian study mostly included patients with small fiber neuropathies, whereas our study was designed to be more inclusive in its selection criteria, given the phenotypic variability and the lack of clear phenotypic description of TTR-FAP in North America." (PMID 32493526, 2020).
tauopathy (3 papers, 2015 to 2025). Neurodegenerative disorders involving deposition of abnormal tau protein isoforms (tau proteins) in neurons and glial cells in the brain. "In view of our results, it is important to unambiguously evaluate the level of TTR in CP epithelial cells and in the CSF of AD and other tauopathies patients." (PMID 41245137, 2025). "The authors found phospho-tau aggregates subjacent to the subpial TTR amyloid deposits in all regions of the neocortex, including the primary motor and striate cortices, and suggest a potential link between TTR amyloid and neocortical tauopathy." (PMID 36198883, 2023).
Thromboembolism (3 papers, 2017 to 2024). The formation of a blood clot inside a blood vessel that subsequently travels through the blood stream from the site where it formed to another location in the body, generally leading to vascular occlusion at the distant site. "In addition to TTR and DJ-1, other plasma proteins (mostly involved in the complement and coagulation systems) were associated with thromboembolism." (PMID 34359938, 2021). "Considering that TTR is upregulated under the hypoxic conditions, TTR upregulation may represent a protective response to thromboembolism." (PMID 34359938, 2021).
tuberculosis (3 papers, 2012 to 2023). A chronic, recurrent infection caused by the bacterium Mycobacterium tuberculosis. "TTR has been suggested as a biomarker for tuberculosis in humans from a study evaluating serum proteomic profiles of patients with active tuberculosis and controls." (PMID 34199073, 2021). "Noteworthy low levels of vitamin A, correlating with reduced TTR and raised concentrations of C-reactive protein, have been reported in patients with tuberculosis." (PMID 23270597, 2012).
acute coronary syndrome (2 papers, 2022 to 2023). Signs and symptoms related to acute ischemia of the myocardium secondary to coronary artery disease. "In patients with acute coronary syndrome, there is an independent negative relationship between transthyretin levels and coronary stenosis." (PMID 36212641, 2022).
autoimmune disease (2 papers, 2022 to 2025). A disorder resulting from loss of function or tissue destruction of an organ or multiple organs, arising from humoral or cellular immune responses of the individual to their own tissue constituents. "TTR, ITIH4, C3, and CRP have been previously reported in the disease pathogenicity and inflammation of autoimmune diseases, affecting synovial joints with restricted joint movements, whereas HP has been linked with irregularity in the homeostasis of free hemoglobin in OA." (PMID 36569927, 2022).
B-cell lymphoma (2 papers, 2025). "CRISPR: clustered regularly interspaced short palindromic repeats; TTR: transthyretin; BCL11A: B-cell lymphoma/leukemia." (PMID 41211267, 2025).
bladder cancer (2 papers, 2013 to 2017). "Previous reports demonstrate that annexin V and transthyretin were downregulated and galectin-1 was increased in bladder cancer." (PMID 23374291, 2013).
brain tumors (2 papers, 2012 to 2022). "Additionally, it effectively transports across the blood-brain barrier via its high-affinity binding to plasma TTR with high retention in brain tumors." (PMID 36879662, 2022). "Interestingly, changes in the relative levels of transthyretin in CSF have been found by SELDI in other biomarker studies of brain tumor." (PMID 23185417, 2012).
cervical carcinoma (2 papers, 2015 to 2022). A carcinoma arising from either the exocervical squamous epithelium or the endocervical glandular epithelium. "A1AT, PYCR2, TTR, ApoAI, VDBP, and MMRN1 were expressed considerably differently in serum samples from healthy controls and cervical cancer patients." (PMID 35645371, 2022).
channelopathies (2 papers, 2020 to 2023). "By detecting 261 genes related to HCM, dilated cardiomyopathy, and other hereditary cardiomyopathies or channelopathies, the heterozygous variation of the TTR gene [NM_000371] was revealed." (PMID 37335747, 2023).
Charcot-Marie-Tooth disease (2 papers, 2011 to 2018). An inherited degenerative disorder involving the peripheral nerves. "Therefore, several clinician-driven registries were deployed during the last 5 years, namely for Charcot-Marie-Tooth disease (CMT), muscle glycogen storage disorders (MGSD), spinal and bulbar muscular atrophy (SBMA), and transthyretin type-familial amyloidotic polyneuropathy (TTR-FAP)." (PMID 30286784, 2018).
demyelinating disease (2 papers, 2020 to 2023). A broad group of disorders that affect the myelin sheaths that cover the neurons. "In cerebrospinal fluid, the specific oxidative modification of TTR Cys10 has been associated with demyelinating diseases." (PMID 37507878, 2023). "How TTR regulates this signaling cascade in oligodendrocytes is of critical importance to understanding its repressive effects upon maturation and myelination, warranting thorough investigation with direct implications to demyelinating diseases." (PMID 32144308, 2020).
focal segmental glomerulosclerosis (2 papers, 2022 to 2025). A renal disorder characterized by sclerotic lesions in the glomeruli. "It was found that fibronectin 1 (FN1), epidermal growth factor (EGF), and transthyretin (TTR) showed considerable diagnostic efficiency for focal segmental glomerulosclerosis, which was based on bioinformatics analysis." (PMID 36199375, 2022).
gout (2 papers, 2020 to 2025). A condition characterized by painful swelling of the joints, which is caused by deposition of urate crystals. "The coordinated alterations in L-thyroxine, ATP1A1, and TTR within the thyroid hormone synthesis pathway suggest hypothalamic–pituitary–thyroid axis involvement, which may influence metabolic and inflammatory processes in gout." (PMID 41511324, 2025).
hereditary ATTR amyloidosis (2 papers, 2021 to 2025). A rare genetic systemic disease characterized by adult onset, progressive sensorimotor and autonomic neuropathy and infiltrative cardiomyopathy. "ATTR amyloidosis can occur due to normal wild-type amyloidogenic TTR (transthyretin) protein or due to a variant of the TTR gene (hereditary ATTR amyloidosis, ATTRv)." (PMID 34703707, 2021).